IL4R (interleukin 4 receptor)
Diseases named in the same sentence as IL4R in open-access papers (continued):
Sharing a sentence is not in itself a finding about the gene and the disease.
tumor (continued). "Tumour cells express elevated levels of IL-4R, and IL-4 signaling reduces cancer cell apoptosis through the upregulation of anti-apoptotic genes while also directly promoting tumour cell proliferation." (PMID 37455828, 2023). "IL4rP, homologous to the sequence of IL4, was earlier shown to selectively target IL4 receptor (IL4R)-expressing tumors by specifically binding to IL4R, a biomarker of tumor cells." (PMID 36839837, 2023). "Human cancer studies have found IL-4R expression to be elevated in many tumours types such as bladder, lung, breast, liver, and prostate cancer, suggesting that IL-4-signalling can be selectively targeted therapeutically for cancer treatment." (PMID 37455828, 2023). "‐Blocking IL‐4 signaling by anti‐IL‐4R delayed tumor growth.‐Prevention of cholesterol efflux by genetic deletion of ABC membrane cholesterol efflux transporters delayed tumor growth." (PMID 36658699, 2023). "Our results showed that the mRNA expression of Rab1A was closely related to the IL-4Rα mRNA expression in GC tumor tissues." (PMID 37117331, 2023). "The relation between tumour growth and IL‐4 has been reported for numerous types of cancer expressing IL‐4 receptor (IL‐4R) including NPC." (PMID 38117000, 2023). "The PERMANOVA analysis revealed that the IHC scores of Rab1A and IL-4Rα significantly differed between tumor and normal tissues (P = 0.001)." (PMID 37117331, 2023). "Systemic administration of IL4R‐Exo (si/mi) showed effective tumor targeting by re‐educating TAM into M1‐type macrophages and promoting the activity of immunostimulatory cells to remodel TME, resulting in inhibited tumor growth." (PMID 37560754, 2023). "In IL4rα-null mutant mice, the initial interactions between tumor cells and monocytes were similar to those observed in WT mice, with an average interaction time of 20.3 ± 3 min (n = 46, p > 0.05)." (PMID 36077870, 2022). "This interaction with wild-type MAMs enhanced tumor cell survival and seeding, which was lost in the IL4rα mice." (PMID 36077870, 2022). "In summary, stage II tumor tissue presented an increase in heparanase and IL-4R, while stage II non-tumor adjacent tissue presented an increase in VEGF-B and the pIκB/IκB ratio." (PMID 36139645, 2022). "PYK2 modulates key signaling pathways mediated by CCL2/CCR2, CXCR4, and IL‐4Rα/pSTAT6, and positively regulates macrophage recruitment and polarization, tumor angiogenesis, and tumor growth." (PMID 35092356, 2022). "The signals of IL4RPep-1-EVsDiD and IL4R were co-localized at the tumor tissues, as revealed by the staining of tumor sections." (PMID 36009525, 2022). "The tumor-targeting capability of EVs was conferred by the engineered IL4R-targeting peptide using a membrane phospholipid-based linker, dioleylphosphatidylethanolamine (DOPE), with a biological anchor for a membrane (BAM)." (PMID 36009525, 2022). "In the current experiments, metrics were developed based upon cell tracking and were used to quantify the number of tumor cell–monocyte and tumor cell–macrophage interactions in WT and IL4rα mutant mice." (PMID 36077870, 2022). "Then, we quantified the time of tumor cell–monocyte and tumor cell–macrophage interactions in WT and IL4rα mutant mice." (PMID 36077870, 2022). "An IL4R-targeting peptide (IL4RPep-1) was labeled onto the surface of EVs, and the ability of IL4Rpep-1-labeled EVs to target the tumor was characterized and evaluated both in vitro and in vivo." (PMID 36009525, 2022). "During tumor development increased expression of interleukin-4 receptor (IL-4R) and elevated IL-4 levels were found in CRC." (PMID 35008550, 2021). "The peptide IL4RPep-1 (CRKRLDRNC) has been shown to bind to IL-4R-expressing tumor cells and M2(IL-4) polarized macrophages." (PMID 34988021, 2021). "It is well known that IL‐4R is not only expressed on 4T1 tumor cells but also expressed on MDSCs and TAMs." (PMID 33682324, 2021).
tumor (continued). "In the ulcerated tumor, B cells showed increased markers associated with type-2 responses such as CCL17, IL4R, and decreases in interferon-stimulated genes (IFI44L, STAT1, IFITM1, MX1, IRF1)." (PMID 34583709, 2021). "In vivo DABIL‐4 markedly inhibited 4T1 tumor growth and metastasis to the lung; however, the primary activity of this fusion protein toxin was found to be the depletion of IL‐4R+ MDSCs, TAM, and Tregs." (PMID 33682324, 2021). "In a similar fashion, we noted an enrichment of TNF‐α+ macrophages in tumor homogenates, while the macrophage population expressing IL‐4R and CD206 were reduced." (PMID 33682324, 2021). "An IL-4Rα aptamer-liposome-CpG oligodeoxynucleotide delivery system was demonstrated to enhance anti-tumor activity in CT26 tumor-bearing mice." (PMID 33450900, 2021). "Related genes that are involved in the formation of IL-13R complex (IL-13Rα1 and IL-4R) and program cell death ligand (PD-L1), as a control, were also evaluated with respect to patient age, hormone production, new tumor events, and tumor metastasis." (PMID 33591997, 2021). "In summary, DABIL‐4 is a promising therapeutic that demonstrates both direct killing of IL‐4R‐positive tumor cells combined with the depletion of IL‐4R‐bearing immunosuppressive cells such as MDSCs and TAMs." (PMID 33682324, 2021). "The expression of IL4Rα was found to be significantly upregulated in OCPs stimulated by tumor conditioned medium (CM)." (PMID 34863091, 2021). "Since IL4/IL4Rα signal was reported to regulate cell proliferation, we next analyzed the expression of IL4Rα in early OCPs during tumor microenvironment." (PMID 34863091, 2021). "It appeared these complexes were internalized by tumor cells via IL-4R mediated endocytosis and then fused with endosomes followed by lysosome where complexes would be degraded and siRNA would be released to cytosol." (PMID 31952530, 2020). "The cell surface antigens were Gr-1hi and IL-4Rαlo in the early tumor stage, and IL-4Rα expression increased from early to late tumor stage." (PMID 32518979, 2020). "IL4R is composed of several distinct chains, on several tumor cells IL4Rα and IL13Rα’ chains are expressed and bind IL4, while in many solid tumor IL13 binds the chains IL-4Rα and IL13Rα1 and IL13Rα2." (PMID 32957689, 2020). "The IL-13Rα2 chain is also highly expressed by several tumor cells and binds with higher affinity to IL-13 than the other chain (IL-13Rα1), even when coupled to IL-4Rα." (PMID 33233582, 2020). "Anti-VCAM1 and anti-IL4Rα aptamers, specific to VCAM-1 and IL4Rα receptors overexpressed in 4T1-Luc2 tumor-bearing mice, were used as diagnostic and therapeutic tools." (PMID 32751068, 2020). "The in vivo therapeutic efficacy evaluated in tumor-bearing mice confirmed the therapeutic efficacy of anti-VCAM-1 and anti-IL4Rα aptamers that were conjugated to SPION as assessed by monitoring tumor growth and inhibition using noninvasive BLI and MRI." (PMID 32751068, 2020). "We suggest the described ELP based systems offer a promising strategy for gene therapy applications that specifically target tumor cells expressing IL4R at high levels." (PMID 31952530, 2020). "Both in vitro cell viability and bioluminescence assays, and in vivo BLI and MRI investigations confirmed that these target specific aptamers effectively blocked the VCAM-1 and IL4Rα signals and suppressed the tumor progression in 4T1-bearing mice." (PMID 32751068, 2020). "IL4 was reported to promote differentiation, proliferation, and survival of different tumor cells through its interaction with IL4R." (PMID 32181251, 2020). "The polymer was highly localized to IL-4R-expressing tumor tissue after intravenous injection and was retained up to 24 h." (PMID 32190533, 2020). "Immunohistological examination of tumor tissues confirmed that Tat-A1E28 and Tat-A4V48 effectively delivered siRNA into tumor tissues, possibly by IL-4R mediated endocytosis and siRNA release." (PMID 31952530, 2020).
tumor (continued). "The AP1 ligand was use to target IL-4R expressing tumor cells, and ELP was chosen due to its stability and thermal sensitivity." (PMID 31952530, 2020). "CD11b+Gr1low cell secretion resulted in an upregulation of IL-4Rα in the tumor microenvironment as compared to healthy brain cells." (PMID 33204365, 2020). "Lastly, IL-4R-targeted liposomal doxorubicin inhibited tumor growth more than chemotherapy in an orthotopic glioma xenograft model." (PMID 33233582, 2020). "Cell viability and luciferase assays showed that both anti-VCAM-1 and anti-IL4Rα aptamers favor the depletion of cancer cells and limit tumor progression." (PMID 32751068, 2020). "In human CCRCC tissue, the expression of IL4Rα and IL13Rα1 were seen in both the cytoplasm and nuclei of tumor cells." (PMID 31540495, 2019). "In fact, our laboratory has been developing the novel drug delivery system using ultrasound and microbubble-liposome complex with IL4RPep-1-K to detect and treat IL4R-expressing tumor." (PMID 31540495, 2019). "RNA aptamer-mediated inhibition of IL4Rα induces apoptosis of MDSC and tumor-associated macrophage (TAM) which is associated with the tumoral immune escape." (PMID 31540495, 2019). "Few cytokines interact with IL4R (especially IL4Rα) results in the enhancement of tumor growth, multiple-drug resistance against apoptosis and differentiation." (PMID 31450709, 2019). "In this model, sildenafil, by lowering MDSCs activity, was sufficient to inhibit IL4Rα expression on MDSCs, reverse T cell anergy, and reduce the number of tumor specific Tregs." (PMID 31214178, 2019). "We have previously shown that tumor cells can interact with muscle stem cells (i.e., satellite cells) in an IL-4R-dependent manner to accelerate tumor progression." (PMID 31113472, 2019). "Optimal activation of tumour-antigen-specific T cells overexpressing IL-4R–IL-7R CSRs occurred only when engineered T cells encountered their specific tumour antigen and elevated IL-4 was present in the tumour microenvironment." (PMID 30413825, 2019). "RMG-I and SAS formed tumor in NOG-hIL-6 Tg mice and flowcytometric analysis demonstrated the induction of CD163+IL-4Rα+TAM-like human myeloid cells as in HSC4-tumor." (PMID 29456539, 2018). "It was found to be over expressed by many human tumor types including malignant glioma, ovarian, lung, breast, pancreatic, colon, and bladder carcinomas, which also overexpress its receptors (IL-4R)." (PMID 28927416, 2017). "In vivo tumor formation and growth of subcutaneously (s.c.)injected clones of control cells N9 and IL-4Rα knockdown cells 2-11, and 3-20 was monitored every 4 days." (PMID 28350325, 2017). "shRNA-based suppression of IL-4Rα in Capan-1 resulted in significantly reduced tumor cell growth in vitro." (PMID 28350325, 2017). "As a predominant glycoprotein of Th2 lymphocytes and mast cells, interleukin-4 receptor (IL-4R) was reported to exist in high amounts in various tumor cells and endothelial cells." (PMID 28938600, 2017). "In various types of cancer including GBM, IL-4Rα, and IL-13Rα1, they have been shown to be overexpressed and promote tumor proliferation, cell survival, and metastasis." (PMID 28752098, 2017). "Targeting IL-4Rα with a fusion protein of IL-4 and Pseudomonas exotoxin resulted in strong anti-tumor activity in vitro as well as in vivo." (PMID 28350325, 2017). "Human tumor cell lines expressing IL-4R has been shown to mediate anti-proliferative activity of IL-4." (PMID 26993600, 2016). "Human tumor cell lines including expressing IL-4R has been shown to mediate anti-proliferative activity of IL-4." (PMID 26993600, 2016). "Several studies have reported that IL-4 is primarily involved in the promotion of differentiation, proliferation, and survival of epithelial tumor cells through its interaction with IL-4Rα." (PMID 27895317, 2016).
tumor (continued). "According to previous reports, IL-4 and IL-4Rα expression are increased in several types of tumor cells, suggesting the involvement of IL-4 in tumor progression and metastasis after IR exposure." (PMID 27895317, 2016). "This suggests that the role of the IL-4/IL-13 axis in the pro-tumor effects of apoptosis is distinct from the IL-4Rα-dependent, alternative macrophage activation pathway." (PMID 25702581, 2015). "To enhance tumor-specific cellular uptake, we connected an interleukin-4 receptor-targeting peptide (I4R) to a nine-arginine peptide (9r), yielding I4R-9r." (PMID 25705892, 2015). "In tumours, IL4Rα expression not only correlates with suppressive function, but can also be used to specifically target MDSC." (PMID 25738302, 2015). "IHC staining of a representative normal, stage I, II, III, and IV tumor for IL-4Rα, IL-13Rα1, and IL-2RγC chain demonstrated an increasing trend of IL-4Rα immunostaining." (PMID 25208941, 2014). "Analysis of tumor biopsy specimens in TMAs revealed significantly higher IL-4Rα immunostaining (≥2+) in Grade 2 (85%) and Grade 3 (97%) compared to Grade 1 tumors (0%) (P ≤ 0.0001)." (PMID 25208941, 2014). "Although IL-4R are expressed in a variety of tumor cells, the significance of expression of these receptors is not known." (PMID 25208941, 2014). "A recent study reported tumor expression of IL-4Rα is inversely correlated with survival in patients undergoing surgical resection for epithelial malignant pleural mesothelioma." (PMID 25208941, 2014). "The second set of TMA of 40 specimens with different clinical stages showed significant overexpression of IL-4Rα in tumor samples with advanced stage disease." (PMID 25208941, 2014). "We observed that mRNA expression for IL-4Rα was significantly higher in all tumor specimens especially those with advanced clinical stage disease compared to 12 normal/noncancerous bladder specimens." (PMID 25208941, 2014). "IHC analyses from tumor and adjacent specimens corroborated the mRNA results and demonstrated overexpression of IL-4Rα and IL-13Rα1 in tumor compared to surrounding tissue." (PMID 25208941, 2014). "Tumour-bearing IL-4Rα−/− mice had fewer CD11b+/Gr1+ myeloid-derived suppressor splenocytes than WT animals." (PMID 23784081, 2013). "The exact target cell that mediates the tumor protective effect upon IL-13 signaling via the IL-4Rα has yet to be defined." (PMID 24403255, 2013). "At least 1 tumour was present in 5 of 14 (26.3%) of WT mice (mean 2 tumours per tumour-bearing mouse) compared with 4 of 16 (25%) of IL-4Rα−/− mice (mean 1.4 tumours per tumour-bearing animal)." (PMID 23784081, 2013). "On the other hand, tumour multiplicity was reduced in IL-4Rα ‘knockout’ mice compared with WT animals in the AOM/dextran sulphate sodium model of CAC." (PMID 23784081, 2013). "IL-4Rα/STAT6 signaling-dependent IL-13 produced by iNKT cells plays an important role in iNKT cell-dependent tumor immunosurveillance." (PMID 23990998, 2013). "The IL-4R dependence of [AP1-V12]6 polymer binding to tumor cells was further confirmed using competition assays." (PMID 24339977, 2013). "IL-4Rα-mediated signalling also plays a role in the host antitumour immune response mediating immunosuppressive activity of tumour-induced myeloid-derived suppressor cells (MDSCs)." (PMID 23784081, 2013). "Counter-intuitively, we also observed a significantly lower apoptosis index (AI) in IL-4Rα−/− tumours compared with WT tumours (P = 0.05; Mann–Whitney U-test)." (PMID 23784081, 2013). "Through activation of the IL-4Rα signaling pathway, these cells increase angiogenesis, promote tumor cell invasion, and inhibit anti-tumor immunotherapy." (PMID 23130020, 2012). "Anti-IL-4Rα aptamer binding leads to depletion of MDSCs and TAMs, which inhibited tumor progression and size in mice." (PMID 23130020, 2012).
tumor (continued). "Contrasting with transplanted tumor models, IL-4Rα expression in spleen of tumor-bearing MT/ret mice is low and similar to the level observed in splenocytes from control mice (data not shown)." (PMID 21633700, 2011). "IL-4 receptor (IL-4R) is an attractive target for immunotherapy because tumor cells express a different IL-4R isoform than that which is present on circulating immune cells." (PMID 22190972, 2011). "Overall, tumor infiltrating myeloid cells are enriched in F4/80+, IL-4Rα+ cells and only a minority of them have the capacity to produce IL-12." (PMID 21633700, 2011). "In MT/ret mice, IL-4Rα is significantly more expressed on tumor infiltrating CD11b+ cells than on their splenic counterparts." (PMID 21633700, 2011). "Combining the staining on tumor and infiltrating cells, a higher incidence of IL-4R positive lesions was observed in patients with longer survival, therefore confirming the findings of the transcriptional analysis." (PMID 17129373, 2006). "In 11 of 27 lesions, tumor cells expressed IL-4R, while in 6 lesions a heterogeneous positive staining was observed also on inflammatory cells permeating the neoplasia." (PMID 17129373, 2006). "Theoretically, IL-4Rα inhibition may reduce type-2 cytokine–mediated tumor-promoting immune suppression, but it could also alter protective immune surveillance, potentially impacting infection risk or anti-tumor immunity in immunocompromised hosts." (PMID 40981274, 2025). "Notably, we provide evidence of substantial Th2 cell infiltration at the bone metastatic site in LUADBM, indicating that Th2 cytokine IL4 activates IL4R signaling in tumor cells, facilitating tumor progression and metastasis." (PMID 39941924, 2025). "Analysis of B- and plasma cells (26,156 cells) showed that germinal centre (GC) B-cells (RGS13+, NEIL1+), cycling B-cells (UBE2C+, TYMS+) and naïve B-cells (TCL1A+, IL4R+) were all enriched in HPV+ve tumours compared to HPV-ve tumours, while switched B-cell subsets were found in both." (PMID 39757146, 2025). "Recent research indicates that, beyond its role in immune functions, the interleukin-4 receptor (IL-4R) is often overexpressed among various cancers and may directly influence several signalling pathways involved in tumour development." (PMID 40544399, 2025). "Notably, systemic IL4R-Exo(si/mi) administration hindered tumor growth, lowered M2 cytokines and immune-suppressive cell levels, and elevated M1 cytokines and immune-stimulatory cell levels, significantly outperforming control exosomes." (PMID 39865337, 2025). "Additionally, IL4 and IL4R interaction enhances the pro-tumorigenic M2-macrophage activity and cathepsin protease production by TAMs 19, 20, which contributes to tumor progression and metastasis." (PMID 38646639, 2024). "Ex vivo imaging of lungs and control organs at 6 h after injection demonstrated that IL4R-Abx accumulated at lungs of K-rasLA2mutant mice bearing tumor nodules at higher levels than at control organs such as the liver, whereas Ctrl-Abx accumulated mostly in the liver." (PMID 38646639, 2024). "IL4R-Abx decreased the tumor volumes, tumor weights, spleen weights or splenomegaly, and the number of metastatic tumor nodules in the lungs more efficiently than Abx and Ctrl-Abx given at a similar dose (5 mg/kg body weight) and Abx given at a higher dose (10 mg/kg body weight)." (PMID 38646639, 2024). "Likewise, an RNA aptamer that blocks the murine or human IL-4receptor-α (IL4Rα or CD124) can promote TAM elimination, an effect that is associated with an increased number of tumor-infiltrating T cells and a reduction in tumor growth." (PMID 36739406, 2023). "Finally, the qPCR helped explore the Rab1A/IL-4Rα mRNA expression in 24 tumor and normal tissue cases, displaying heatmap." (PMID 37117331, 2023). "Additionally, interleukin 4 receptor (IL4R)-binding peptide (IL4rP) (CRKRLDRNC) was ligated to the C-terminal end as a tumor-targeting peptide moiety." (PMID 36839837, 2023).